GJB2 (gap junction protein beta 2)
Diseases named in the same sentence as GJB2 in open-access papers (continued):
Sharing a sentence is not in itself a finding about the gene and the disease.
psoriasis (continued). "Additionally, GJB2 may be involved in the development and progression of psoriasis by disrupting the body's immune system, mediating the cell cycle, and destroying the skin barrier, in addition to possibly inducing diseases related to the skeletal aspects of psoriasis." (PMID 36193416, 2022).
cystic fibrosis (13 papers, 2015 to 2025). Autosomal recessive disorder caused by pathogenic variants in the CFTR gene (cystic fibrosis transmembrane conductance regulator), which encodes a chloride and bicarbonate channel expressed in epithelial cells, and follow the diagnosis criteria. "This is exemplified by the most frequent CFTR pathogenic variant NM_000492.3:c.1521_1523del; p.(Phe508del) in cystic fibrosis (MAF~0.015 in Non-Finnish Europeans) and the GJB2 variant NM_004004.5:c.35del; p.(Gly12ValfsTer2) in non-syndromic sensorineural deafness (MAF~0.01 in Non-Finnish Europeans)." (PMID 39201349, 2024).
Usher syndrome (11 papers, 2006 to 2025). A syndromic diseae characterized by the association of sensorineural deafness (usually congenital) with retinitis pigmentosa and progressive vision loss. "In our study, we identified carriers of Pendred syndrome, Usher syndrome, and GJB2 (nonsyndromic hereditary neurosensory hearing loss) to be common in the Thai cohort, aligning with previous estimations." (PMID 38167091, 2024). "For example, GJB2 encodes the gap junction protein connexin 26, while many of the genes in Usher syndrome such as MYO7A and WHRN encode for essential hair bundle components." (PMID 38137568, 2023). "Children with severe-to-profound bilateral hearing loss would be more likely to have vestibular dysfunction, and some etiologies, such as Usher syndrome, congenital CMV infection, and GJB2 gene mutations, would also be more closely related to vestibular deficits." (PMID 39442262, 2024).
hepatocellular carcinoma (10 papers, 2013 to 2025). A malignant tumor that arises from hepatocytes. "GJB2 has been shown to drive hepatocellular carcinoma progression by fostering an immunosuppressive tumor microenvironment." (PMID 40575171, 2025). "To further confirm this conclusion, we also used immunofluorescence to detect the expression and localization of GJB2 protein in organoids‐cultured mouse hepatoma cells and normal liver cells." (PMID 39162005, 2024).
Hyperkeratosis (10 papers, 2020 to 2026). Hyperkeratosis is a histopathological term defining a thickened stratum corneum and may be present in many different skin conditions, with many possible overlaps. "All of the skin diseases caused by GJB2 gene mutations are commonly related to hyperkeratosis (especially palmoplantar hyperkeratosis) and mainly exhibit autosomal dominant inheritance." (PMID 35457072, 2022). "Hereditary mutations in the GJB2 gene of connexin 26 are a basis of mutilation syndromes of sensorineural deafness, hearing loss and hyperkeratosis with autosomal recessive (DFNB1) and autosomal dominant (DFNA3) types of inheritance." (PMID 34512926, 2021). "Syndromic HHI with hyperkeratosis are caused by pathogenic variants in two gap junction genes, GJB2 and GJB6, which encode connexins that are key to intercellular signaling." (PMID 33396879, 2020). "GJB2 causal mutations precipitate the excessive opening of the Cx26 hemichannel, rendering it insensitive to the intra-epidermal variation in pH, and thus enabling the leakage of biomolecules that results in the increased proliferation of keratinocytes (hyperkeratosis)." (PMID 36986378, 2023).
pancreatic cancer (10 papers, 2015 to 2025). "High expression of GJB1 and GJB2 was also associated with lymph node metastasis and prognosis in carcinoma of the pancreas." (PMID 40575171, 2025). "GJB2 is implicated in the mechanisms of invasion of ductal breast carcinoma and it is a prognosis marker in pancreatic cancer." (PMID 31182966, 2019). "GJB2 facilitated pancreatic cancer development by releasing ATP through the hemichannels, thereby promoting inflammation by activating the leukocytes." (PMID 37427102, 2023). "The GJB2-positive CAFs showed the highest abundance in pancreatic cancer among the 24 cancer types from The Cancer Genome Atlas and the various scRNA-seq datasets." (PMID 37648762, 2023). "In particular, the poor prognosis of cancers with high GJB2-positive signatures, including pancreatic cancer, suggests that GJB2-positive CAFs play an important role in fibrosis and clinical outcomes." (PMID 37648762, 2023). "The result showed that high expression level of COL11A1, GJB2 or low expression level of CTRL in pancreatic cancer tissue sections indicated poorer prognosis and less survival rate." (PMID 30410422, 2018). "Kaplan-Meier survival analysis revealed that GJB2 and ERO1LB levels were significantly associated with the overall survival of pancreatic cancer patients." (PMID 28177904, 2017). "GJB2 and ERO1LB are implicated in pancreatic cancer progression and can be used to predict patient survival." (PMID 28177904, 2017). "Additionally, the low GJB2 expression in cultured CAFs from pancreas cancer tissues suggests that the expression of GJB2 is dependent on interactions with other cells, including vascular endothelial cells and cancer cells." (PMID 37648762, 2023). "verified that GJB2 expression was higher in pancreatic cancer than in para-cancerous tissue." (PMID 35936685, 2022). "GJB2 was also suggested as a prognostic marker in pancreatic cancer." (PMID 32228510, 2020). "We further asked whether the elevated expression of GJB2 or down-regulated ERO1LB levels in pancreatic cancer could affect patient survival." (PMID 28177904, 2017). "Results of bioinformatic analysis and IHC analysis suggested that COL11A1, GJB2 and CTRL are novel predictive biomarkers for pancreatic cancer." (PMID 30410422, 2018). "We validated the expression level of COL11A1, GJB2 and CTRL with IHC assay of 46 paired pancreatic cancer and para-cancerous tissue sections." (PMID 30410422, 2018). "COL11A1, GJB2 and CTRL are novel predictive biomarkers for pancreatic cancer." (PMID 30410422, 2018). "Furthermore, no published paper evaluated the expression and predictive value of COL11A1, GJB2 and CTRL in pancreatic cancer." (PMID 30410422, 2018). "Therapeutic strategies targeting GJB2 and facilitating ERO1LB expression may deserve evaluation to improve prognosis of pancreatic cancer patients." (PMID 28177904, 2017). "GJB2 and ERO1LB levels were shown to have prognostic significance and therapeutic strategies targeting GJB2 and facilitating ERO1LB expression may deserve evaluation to improve prognosis of pancreatic cancer patients." (PMID 28177904, 2017). "Finally, we selected and validated the clinical predictive value of COL11A1 (collagen alpha-1(XI) chain), GJB2 (gap junction beta-2 protein) and CTRL (chymotrypsin-like protease CTRL-1) with immunohistochemical (IHC) analysis of 46 paired pancreatic cancer and para-cancerous tissue sections." (PMID 30410422, 2018). "GJB2 was chosen as dysregulation of gap junction proteins is closely correlated with cancer progression and there was no published papers regarding the role of GJB2 in pancreatic cancer." (PMID 30410422, 2018).
Vohwinkel syndrome (10 papers, 2011 to 2025). "For example, Vohwinkel Syndrome is an autosomal dominant syndromic disease caused by mutations in the GJB2 gene encoding Cx26 and is characterized by sensorineural deafness, palmoplantar hyperkeratosis, and pseudoainhum." (PMID 31817921, 2019). "Among them, Vohwinkel syndrome was the first of the known skin diseases to be attributed to a mutation in GJB2 (c.G196C leading to p.Asp66His)." (PMID 27141831, 2016). "However, its role in Vohwinkel syndrome in relation to the gap junction protein beta 2 (GJB2) mutation is still unclear." (PMID 36916028, 2023).
glioma (9 papers, 2013 to 2026). A benign or malignant brain and spinal cord tumor that arises from glial cells (astrocytes, oligodendrocytes, ependymal cells). "Interestingly, here we detected two ClinVar LP/P GJB2 GVs in three glioma patients, newly implicating pathogenic GVs in GJB2 in glioma risk." (PMID 41546701, 2026). "Other gene functions implicated in glioma risk in this study include signal transduction (e.g. EGFR), cell adhesion (e.g. GJB2), immune response (e.g. IFIH1 and SAMHD1), and ion transport (e.g. CFTR)." (PMID 41546701, 2026). "Specificity of expression for connexin genes in astrocytic cells, GJA1/Cx43, GJB6/Cx30, and GJB2/Cx26, was used to verify expected cells of origin for the glial tumors, oligodendrogliomas, and glioblastomas in REMBRANDT patients on anti-seizure drugs." (PMID 40867621, 2025). "We validated the survival associations of GJB2 and SCN9A expression in two independent GBM cohorts, including 136 samples from the Glioma Longitudinal Analysis (GLASS) and 55 samples from an earlier microarray dataset." (PMID 38177502, 2024). "High GJB2 expression is associated with worse prognosis in GBM and LGG, suggesting common mechanisms in high- and low-grade gliomas." (PMID 38177502, 2024). "Besides GBM, GJB2, and SCN9A expression associated with poor prognosis in low-grade glioma, kidney, and uterine cancer, lending further confidence to these genes." (PMID 38177502, 2024). "The CPGs most frequently affected by GVs were ATM in 6/206 (2.9%) families, BRCA2 in 5/206 (2.4%) families (identified in approaches 1 and 2), GBA1 in 4/206 (1.9%) families as well as EGFR, GJB2, and SDHA in 3/206 (1.5%) families each of the glioma cohort." (PMID 41546701, 2026). "Higher GJB2 expression in differentiated cells was characteristic of IDH-wildtype GBMs with worse prognosis, while reduced GJB2 expression and enrichment of stem-like cells was apparent in IDH-mutant gliomas with improved prognosis." (PMID 38177502, 2024).
syndromic (9 papers, 2011 to 2025). "Moreover, genetic variants in the gap junction beta 2 (GJB2), more commonly known as connexin 26, have been found to cause autosomal recessive non-syndromic uSNHL." (PMID 36675424, 2023). "Moreover, it has been demonstrated that connexins are involved in regulation of growth and differentiation of epidermis and, in fact, GJB2 mutations have also been identified in syndromic disorders with hearing loss associated with various skin disease phenotypes." (PMID 22547955, 2011). "Other alterations included compound GJB2/GJB6 mutations, DIABLO gene variants, and Down syndrome (n = 2 each, 2.4%)." (PMID 41303275, 2025). "In our cohort, two children were identified with multiple possible causes for SNHL: in one child, a cochlear nerve aplasia was found as well as a GJB2 gene variant, in the other, a congenital CMV infection was identified as well as Down syndrome." (PMID 31152317, 2019).
lung adenocarcinoma (8 papers, 2019 to 2024). A carcinoma that arises from the lung and is characterized by the presence of malignant glandular epithelial cells. "GJB2 encodes gap junction binding protein 2, a connexin which plays roles in epithelial barrier integrity and is known for its importance in lung adenocarcinoma." (PMID 39395995, 2024). "While some have been identified as tumor suppressors, we found that high expression of GJB2/3/5 was linked to worse survival in the TCGA lung adenocarcinoma RNA-seq dataset (p < 0.001)." (PMID 32822576, 2020). "Firstly, observe the prognostic significance and the biological functional effects of gap junction protein beta 2 (GJB2 or Cx26) in lung adenocarcinoma (LUAD)." (PMID 37188183, 2023). "Moreover, we evaluated the prognostic significance of high GJB2 expression in the lung adenocarcinoma (LUAD) cohort from The Cancer Genome Atlas (TCGA)." (PMID 39737401, 2024). "First because GJB2, expressed by tumor cells and cancer-associated fibroblasts (CAFs), contributes to ECM remodeling and activates the SPP1/PI3K/AKT signaling pathway in lung adenocarcinoma." (PMID 39737401, 2024).
Pendred syndrome (8 papers, 2006 to 2025). Pendred syndrome (PDS) is a clinically variable genetic disorder characterized by bilateral sensorineural hearing loss and euthyroid goiter. "Genetic causes included autosomal recessive non-syndromic hearing loss (GJB2/connexin 26), Townes–Brocks syndrome (SALL1), Pendred syndrome (SLC26A4) and Chromosome 8P inverted duplication and deletion syndrome, and CHARGE syndrome (CHD7)." (PMID 36675424, 2023). "The causes were autosomal recessive non-syndromic hearing loss (GJB2), Townes–Brocks syndrome (SALL1), Pendred Syndrome (SLC26A4), Chromosome 8P inverted duplication and deletion syndrome, and CHARGE syndrome (CHD7)." (PMID 36675424, 2023). "Genetic causes for the uSNHL were found in 28% of subjects (5/18) including CHARGE syndrome (CHD7), autosomal recessive non-syndromic hearing loss (GJB2), Townes–Brocks syndrome (SALL1), Pendred Syndrome (SLC26A4) and Chromosome 8P inverted duplication and deletion syndrome." (PMID 36675424, 2023). "Similarly to GJB2-related uSNHL, Pendred syndrome (about 1 in 10,000–20,000 births) has mostly been associated with bilateral SNHL, not uSNHL." (PMID 36675424, 2023). "The testing included family history, karyotyping, analysis of selected ethnicity-related genes (such as GJB2, GJB6), a Pendred syndrome panel (SLC26A4 gene), and others." (PMID 40283619, 2025).
prostate carcinoma (8 papers, 2013 to 2024). A carcinoma that arises from epithelial cells of the prostate gland. "Mutations of GJB2 (coding Cx26) might be associated with an increased propensity to develop skin cancer; and germline mutations of this gene are assumed to increase the risk for early onset prostate cancer." (PMID 36829482, 2023). "GJB2, MET, MUTYH and VHL mutations ranked top in kidney cancers, and ATM and CHEK2 mutations ranked top for bladder cancer, while ATM and BRCA1 mutations ranked top for prostate cancer." (PMID 36451132, 2022).
glioblastoma (7 papers, 2015 to 2025). The most malignant astrocytic tumor (WHO grade IV). "GJB1 and GJB2 are highly expressed in glioblastoma and PC, which are closely related to chemotherapy resistance." (PMID 40575171, 2025). "Notably, GJB2 and SCN9A show prominent expression in neoplastic cells and are associated with poor prognosis in glioblastoma, the most common and aggressive brain cancer." (PMID 38177502, 2024). "Interestingly, we found the GJB2 (also known as connexin 26): RTN4 (also known as NOGO) pair in the CTmvp signature, with both genes being indicative of poor prognosis in glioblastoma." (PMID 33927352, 2021).
presbycusis (7 papers, 2018 to 2024). Bilateral hearing loss caused by progressive degeneration of cochlear structures and central auditory pathways, typically associated with the aging process. "Hypermethylation of GJB2 promoter region in the mimetic aging rat cochlea was associated with down regulation of connexin 26 that resulted in the development of presbycusis." (PMID 30131691, 2018). "Some cases of presbycusis emerge more prematurely, maybe it is due to decrease of GJB2 expression by a cis-regulatory variants and correlates with environment factors." (PMID 34440441, 2021).
autosomal recessive deafness type 1A (6 papers, 2019 to 2024). "GJB2-associated autosomal recessive deafness type 1A was the only condition in which biallelic mutations were identified in the same person (n = 22) in the study cohort." (PMID 35314707, 2022). "The most prevalent variant in our cohort was GJB2 c.109G>A, which is associated with autosomal recessive deafness type 1A." (PMID 35314707, 2022). "Mutations in the GJB2 gene are the main cause for nonsyndromic autosomal recessive deafness 1A (DFNB1A) in many populations." (PMID 31195736, 2019). "As the result of sequencing the GJB2 coding (exon 2) and non-coding (exon 1) regions with flanking sequences, a genetic diagnosis “Nonsyndromic autosomal recessive deafness 1A (DFNB1A)” due to the presence of biallelic GJB2 pathogenic variants was established for 22.3% (49 out of 220) patients." (PMID 31195736, 2019). "Autosomal recessive nonsyndromic hearing loss 1A (DFNB1A, OMIM 220290), caused by pathogenic variants in the GJB2 gene (13q12.11, OMIM 121011), is considered to be the most common form of HL in many global populations." (PMID 36362242, 2022). "Thus, the proportion of pathogenic biallelic variants of the GJB2 gene (13q11-q12) encoding the intercellular gap junction protein connexin 26 (Cx26) leading to autosomal recessive deafness type 1A (DFNB1A, OMIM #220290) is significant, and in some populations, it is up to 50–60%." (PMID 39436953, 2024).
hearing (6 papers, 2014 to 2025). "Both the patient’s parents and her brother (cases 4–6) experienced hearing impairment due to a combination of a mutation in the heterozygosity of GJB2 [(GJB2-c.35 delG)] and GJB6 [del(GJB6-D13S1830)]." (PMID 40504319, 2025). "The mutation of p.Leu79Cysfs*3, the most prevalent GJB2 gene mutation in Asia, has recently been linked to a diverse range of hearing loss degrees." (PMID 38069086, 2023). "Phenotypically, two probands carrying del(125 kb) and GJB2 c.109G>A (p.Val37Ile) exhibited mild-to-moderate hearing loss (F10 II-1 and F34 II-1), while the other proband (F43 II-1) carrying del(GJB6-D13S1854) and GJB2 c.299_300del (p.His100ArgfsTer14) presented with profound hearing loss." (PMID 40225913, 2024).
liver cancer (6 papers, 2013 to 2024). An epithelial or non-epithelial malignant neoplasm that arises from the liver. "The results showed that the expression of GJB2 protein in liver cancer cell membrane was lower than that in normal liver cells, while the expression in cytoplasm and nucleus was higher than that in liver cells, which was consistent with the conclusion of human samples." (PMID 39162005, 2024).
lung cancer (6 papers, 2019 to 2024). A malignant neoplasm involving the lung. "All these data suggested that aberrant GJB2 expression is associated with tumor progression in lung cancer." (PMID 35196203, 2022). "The database identifies GJB2 as significantly associated with poor prognosis in lung cancer (p = 6.25 × 10−4)." (PMID 30845770, 2019). "Moreover, we revealed that GJB2 was significantly upregulated in lung cancer, and patients with a higher level of GJB2 exhibits poor overall survival." (PMID 35196203, 2022).
phenylketonuria (6 papers, 2020 to 2025). Phenylketonuria (PKU) is the most common inborn error of amino acid metabolism and is characterized by mild to severe mental disability in untreated patients. "Furthermore, 16 individuals were found to be homozygous or compound heterozygous for the following conditions: hepatolenticular degeneration (n = 10), GJB2-related non-syndromic hearing loss (n = 3), phenylketonuria (n = 1), and CAH (n = 2)." (PMID 35079019, 2022). "More recently, TLA has also been applied to methylmalonic acidaemia (MMACHC), α- and β-thalassaemia (HBA, HBB), phenylketonuria (PAH), polycystic kidney disease (PKHD1), and autosomal recessive non-syndromic hearing loss (GJB2)." (PMID 39698301, 2023).
Sensorineural hearing impairment (6 papers, 2010 to 2022). A type of hearing impairment in one or both ears related to an abnormal functionality of the cochlear nerve. "Mutations in the gap junction protein β-2 (GJB2) gene encoding connexin 26 (Cx26) are the most common cause of sensorineural hearing impairment." (PMID 33187328, 2020). "GJB2 mutations among 365 previously studied and 97 Ghanaians families with profound sensorineural hearing impairment." (PMID 31620164, 2019). "In about 6% of Chinese patients with severe to profound sensorineural hearing impairment, only monoallelic GJB2 mutations known to be either recessive or of unclear pathogenicity have been identified." (PMID 21122151, 2010). "In this study, we identified 7 families, 11 subjects with dominant GJB2 mutations by sequencing of GJB2 in 2168 Chinese Han probands with sensorineural hearing impairment and characterized the associated spectrum, de novo rate and genotype-phenotype correlation." (PMID 24945352, 2014).